COL6A5 (collagen type VI alpha 5 chain)
Description:
Collagen VI acts as a cell-binding protein.
Synonyms: COL29A1; VWA4; FLJ35880
Tractability: Antibody: its Gene Ontology location is reachable by antibodies, with high confidence; UniProt places it where antibodies can reach, with medium confidence; UniProt predicts a signal peptide or a membrane-spanning region. PROTAC: ubiquitination databases record sites on it. Other modalities: an approved drug acts on it.
Gene: Protein-coding gene on chromosome 3 (130,345,516 to 130,484,846, forward strand). Ensembl gene ENSG00000172752.
Subcellular location: Secreted, extracellular space, extracellular matrix
Pathways (Reactome):
Extracellular matrix organization: Assembly of collagen fibrils and other multimeric structures; Collagen biosynthesis and modifying enzymes; Collagen chain trimerization; Collagen degradation; ECM proteoglycans; Integrin cell surface interactions
Developmental Biology: NCAM1 interactions
Signal Transduction: Signaling by PDGF
Gene Ontology:
Molecular function: extracellular matrix structural constituent conferring tensile strength; protein binding
Biological process: extracellular matrix organization
Cellular component: extracellular matrix; extracellular region; collagen type VI trimer
Genetic constraint (gnomAD): Loss-of-function variants: 38 observed, 54.58 expected, observed/expected ratio (o/e) 0.7, 90% interval 0.54 to 0.91. The upper end of that interval is the gene's LOEUF score, 0.91, which puts it in group 3 of 6, group 1 being the genes least tolerant of losing a copy. Missense variants: 861 observed, 916.47 expected, observed/expected ratio (o/e) 0.94, 90% interval 0.89 to 0.99. Synonymous variants: 269 observed, 322.88 expected, observed/expected ratio (o/e) 0.83, 90% interval 0.75 to 0.92.
Homologues: Orthologues: chimpanzee COL6A5 (98% identical), macaque COL6A5 (92% identical), rabbit COL6A5 (76% identical), dog COL6A5 (75% identical), mouse Col6a5 (73% identical), rat Col6a5 (72% identical), guinea pig COL6A5 (71% identical), pig COL6A5 (67% identical), Caenorhabditis elegans mup-4 (10% identical), Caenorhabditis elegans C29A12.6 (5% identical). Paralogues in human: COL6A6 (47% identical), COL6A3 (27% identical), COL12A1 (14% identical), COL14A1 (12% identical), VWA2 (6% identical), MATN2 (6% identical), MATN4 (5% identical), MATN1 (5% identical), VIT (4% identical), COCH (4% identical), MATN3 (3% identical), VWA1 (3% identical).
Diseases named in the same sentence as COL6A5 in open-access papers:
COL6A5 is named in the same sentence as 43 diseases in open-access papers, as found by Europe PMC text mining. Sharing a sentence is not in itself a finding about the gene and the disease. The quoted sentences say what the papers report.
atopic dermatitis (12 papers, 2009 to 2024). "Human α5 was found to be localized in the outer epidermis and COL6A5 has been associated with atopic dermatitis and designated COL29A1." (PMID 36500453, 2022). "Eight variants located in COL6A5 gene have been demonstrated to be related to the susceptibility to atopic dermatitis among Europeans37." (PMID 32193401, 2020). "Furthermore, single nucleotide polymorphisms within the COL3A1 and COL6A5 genes have been associated with atopic dermatitis, revealing distinct genotype-phenotype relationships." (PMID 38404668, 2024). "Interestingly, the COL6A5 gene had previously been reported as associated with atopic dermatitis under the name COL29A1, but this association has recently been questioned." (PMID 21943391, 2011). "Proinflammatory FB populations have been recently described in other inflammatory skin diseases, including Th2 responsive COL6A5+COL18A1+ FBs in atopic dermatitis and T cell–attracting CXCL9/CXCL10-expressing FBs in vitiligo." (PMID 37471168, 2023). "In addition, the SFRP2+ inflammatory fibroblasts in psoriasis share with the COL6A5+COL18A1+ fibroblasts in atopic dermatitis the expression of CCL19 which is capable of recruiting CCR7+LAMP3+ cDC2A61." (PMID 37308489, 2023). "The link between COL6A5 and atopic dermatitis is controversial, but a mechanism involving HERV-K (HML-2) integration, such as alternative splicing or the generation of antisense RNA, might resolve this conflict." (PMID 32375827, 2020). "It was found that COL6A5 fibroblasts existed in atopic dermatitis skin, but not in healthy tissues." (PMID 35096002, 2021).
gastric cancer (6 papers, 2021 to 2025). A primary or metastatic malignant neoplasm involving the stomach. "The elevated USP3 expression can affect the abundance of COL9A3 and COL6A5, thereby promoting tumor proliferation and migration of gastric cancer cells." (PMID 39759114, 2025). "The deubiquitination enzyme USP3, an essential mediator regulating oncogenic activity both in vitro and in vivo, can deubiquitinate COL9A3 and COL6A5 in gastric cancer cells." (PMID 39759114, 2025). "USP3 can accelerate gastric cancer metastasis by enhancing the COL9A3/COL6A5 stability via deubiquitination." (PMID 37980532, 2023). "USP3 regulates COL9A3/COL6A5 stabilisation to promote gastric cancer progression." (PMID 36766336, 2023). "Similarly, USP3 was reported to promote the gastric cancer progression and metastasis by deubiquitinating COL9A3 and COL6A5." (PMID 37322017, 2023).
asthma (4 papers, 2009 to 2023). "Furthermore, it has been reported that variations in COL6A5 might play causal roles for asthma together with environmental exposures." (PMID 32193401, 2020). "In our study, we have investigated the association of SNPs in three collagen-coding genes, Col3A1/rs1800255, Col6A5/29rs12488457, and Col8A1/rs13081855, with the clinical manifestations of AD as well as the coexistence of asthma." (PMID 37109047, 2023). "But a recent study has not found any significant relationships between COL6A5 variants and asthma or chronic obstructive pulmonary disease in German41." (PMID 32193401, 2020).
psoriasis (4 papers, 2020 to 2023). An autoimmune condition characterized by red, well-delineated plaques with silvery scales that are usually on the extensor surfaces and scalp. "This suggests a potential contribution of COL6A5 to the etiopathogenesis of psoriasis." (PMID 37047652, 2023).
lung carcinoma (3 papers, 2020 to 2021). "The current study evaluated the correlations between polymorphisms in COL6A5 gene and lung cancer susceptibility among Chinese Han individuals." (PMID 32193401, 2020). "COL6A5 rs13062453, rs1497305, and rs77123808 were significantly associated with the risk of lung cancer in the whole population or stratified subgroups (p < 0.05)." (PMID 32193401, 2020). "We found that COL6A5 rs13062453, rs1497305, and rs77123808 were associated with the risk of lung cancer in Chinese Han population." (PMID 32193401, 2020). "Second, we examinated the associations of COL6A5 SNPs with two common pathological types of lung cancer, namely lung adenocarcinoma and squamous cell carcinoma." (PMID 32193401, 2020). "In summary, this is the first research that discussed the relationships between COL6A5 polymorphisms and lung cancer risk." (PMID 32193401, 2020). "In our study, COL6A5 polymorphisms rs13062453, rs1497305, and rs77123808 were genetic polymorphic markers that confer susceptibility to lung cancer among Chinese Han individuals." (PMID 32193401, 2020). "We performed a genetic association study with an attempt to detect the relationships between single nucleotide polymorphisms (SNPs) in COL6A5 and lung cancer predisposition in Chinese Han population." (PMID 32193401, 2020). "Third, the underlying mechanism of the promising SNPs and COL6A5 gene in lung cancer development is still unclear, thus suggesting the nest step for the further research." (PMID 32193401, 2020). "COL6A5 polymorphisms rs13062453, rs1497305 and rs77123808 were associated with lung cancer risk in Chinese Han population." (PMID 32193401, 2020). "COL9A3 might be correlated with the pathogenesis of triple-negative breast cancer, and the polymorphisms of COL6A5 might be relevant to lung cancer susceptibility among Chinese Han individuals." (PMID 34930901, 2021). "Abundant type vicollagen in lung tissue α5 (COL6A5), rs13062453, rs1497305, and rs77123808 of COL6A5 polymorphism are associated with lung cancer risk in Chinese Han population, and the overall survival rate of patients with low expression of the COL6A5 gene is poor." (PMID 35096002, 2021). "Accordingly, we hypothesized that the single nucleotide polymorphisms (SNPs) in COL6A5 might be associated with lung cancer risk, and performed a genetic association study to investigate the relationships between the COL6A5 variations and lung cancer predisposition among Chinese Han population." (PMID 32193401, 2020). "Results from databases suggested the important role of COL6A5 in lung cancer development." (PMID 32193401, 2020). "The abundant expression of collagen type VI α5 (COL6A5) exists in lung tissue, and its role in lung cancer is still unknown." (PMID 32193401, 2020). "Additionally, COL6A5 rs1497305 was found to be associated with TNM staging, which harbors the potential to become new target for lung cancer clinical stage evaluation in future." (PMID 32193401, 2020). "However, the characteristics of COL6A5 gene in lung cancer remains incompletely understood." (PMID 32193401, 2020).
giant cell arteritis (2 papers, 2016 to 2021). "Some studies have found a link between COL6A5 variants, reduced bone mass, dyspnea, and giant cell arteritis." (PMID 35096002, 2021). "Like rs113396273, the other SNPs tested in COL6A5 demonstrated similar patterns of associations including respiratory abnormalities and giant cell arteritis." (PMID 26833085, 2016).
Obesity (2 papers, 2013 to 2023). Accumulation of substantial excess body fat. "Highly downregulated genes at day 1 included genes associated with obesity including Col6a5 (collagen type VI alpha 5 chain), Fgg (Fibrinogen Gamma Chain), and adipokines Lcn2 (Lipocalin 2) and Retn (resistin) 32–34." (PMID 37770553, 2023). "Expression of Col6a5 in adipose tissue is associated with obesity, and insulin resistance." (PMID 37770553, 2023). "Moreover, some of the down-regulated genes including Col6a5 and Fgg are associated with obesity." (PMID 37770553, 2023). "A larger sample size is necessary to further elucidate this coexistent condition and to determine whether COL6A5 has any role in obesity related conditions." (PMID 24348519, 2013).
cartilage disorders (1 paper, 2016). "We performed a matched PheWAS in human using the BioVU resource and linked rs113396273 in exon 3 of COL6A5 (M56T) with osteopenia and other bone and cartilage disorders (P=1.4 × 10−3; logistic regression)." (PMID 26833085, 2016).
colon cancer (1 paper, 2024). "Currently, COL6A5 gene has been associated with lipid metabolism, proliferation and angiogenesis of colon cancer cells." (PMID 39739914, 2024).
dermatitis (1 paper, 2020). An inflammatory process affecting the skin. "Type 6 collagen 5 chain (COL6A5) is also known as COL29A1, and its variation is closely associated with specific dermatitis." (PMID 32508922, 2020).
esophageal squamous cell carcinoma (1 paper, 2021). Esophageal squamous cell carcinoma (ESCC) is a type of esophageal carcinoma (EC) that can affect any part of the esophagus, but is usually located in the upper or middle third. "It has been confirmed that the COL6A5 gene is significantly associated with the overall survival rate of patients with esophageal squamous cell carcinoma (ESCC)." (PMID 35096002, 2021).
Hernia (1 paper, 2023). "Quantitative real-time PCR was performed for MMP13, VIT, ACAN, and COL6A5 in muscle and connective tissue for all 68 animals, revealing differences in the mRNA level of MMP13 and VIT between the control and hernia pigs." (PMID 37895252, 2023).
lipid metabolism disorder (1 paper, 2021). "Our results indicate that Col6a5 plays important roles in the pathogenesis of DHT-induced lipid metabolism disorder and the hypertrophy of ovarian stromal cells and adipocytes." (PMID 34109177, 2021). "We hypothesize that androgen acts directly on ovarian cells and adipocytes, leading to lipid metabolism disorder and hypertrophy, which can be ameliorated by Col6a5 suppression." (PMID 34109177, 2021).
lung adenocarcinoma (1 paper, 2020). A carcinoma that arises from the lung and is characterized by the presence of malignant glandular epithelial cells. "Among them, COL6A5 rs13062453 and rs1497305 were also linked to the susceptibility of lung adenocarcinoma." (PMID 32193401, 2020). "Overall, COL6A5 was down-regulated in both lung adenocarcinoma and lung squamous cell carcinoma." (PMID 32193401, 2020).
lymph node metastasis (1 paper, 2020). "Lastly, the contributions of COL6A5 variants on TNM staging and lymph node metastasis were demonstrated." (PMID 32193401, 2020).
cancer (5 papers, 2019 to 2022). A tumor composed of atypical neoplastic, often pleomorphic cells that invade other tissues. "The COL6A5 gene is not only associated with skin inflammation, but also with cancer." (PMID 35096002, 2021). "Semi-quantitative scoring showed that USP3, COL9A3 and COL6A5 proteins were expressed at significantly higher levels in cancer tissues than in adjacent normal tissues." (PMID 34930901, 2021). "However, there are few reports on the relationship between COL9A3/COL6A5 and cancer." (PMID 34930901, 2021).
tumor (5 papers, 2019 to 2022). "We also observed that higher expression of USP3 was associated with stronger expression of COL9A3 and COL6A5 in tumour tissues." (PMID 34930901, 2021). "To further investigate the effects of the USP3-COL9A3/COL6A5 axis on tumour metastasis in GC in vivo, we established BGC-823 cells stably depleting USP3 by lentiviral transfection, with simultaneous overexpression of COL9A3 or COL6A5." (PMID 34930901, 2021). "Among them, the expression of COL1A1, COL10A1 and COL11A1 was particularly higher, and that of COL4A4, COL6A5 and COL14A1 was especially lower in tumor tissues, indicating their possible roles as diagnostic markers for ESCC." (PMID 31598423, 2019). "Moreover, we further analysed USP3, COL9A3 and COL6A5 expression in tumour samples and adjacent normal tissues from 94 GC patients using TMA, along with their corresponding clinicopathologic information." (PMID 34930901, 2021). "We thus speculated that COL6A5 functions as a tumor suppressor gene in oncogenesis of lung." (PMID 32193401, 2020). "We collected tumour tissues and corresponding normal tissues of gastric mucosa from 12 GC patients and detected the expression of USP3, COL9A3, and COL6A5 by western blotting." (PMID 34930901, 2021). "As members of the collagen family, COL9A3 and COL6A5 serve as essential skeletons in the extracellular matrix (ECM), which is the major component of the tumour microenvironment." (PMID 34930901, 2021). "Among them, the expression of COL1A1, COL10A1, and COL11A1 were found to be particularly high in tumor tissues compared with normal counterpart; on the contrary, the expression of COL4A4, COL6A5 and COL14A1 was significantly lower in tumor tissues." (PMID 34199373, 2021).
infection (1 paper, 2016). The state of being infected such as from the introduction of a foreign agent such as serum, vaccine, antigenic substance or organism. "Among them, 25 genes, such as arachidonate 15-lipoxygenase (ALOX15), collagen, type VI, α5 (COL6A5), and serglycin (SRGN), were significantly upregulated while the expression of transthyretin (TTC) was repressed by infection." (PMID 27197554, 2016).
myopathy (1 paper, 2022). A disease of the muscle in which the muscle fibers do not function properly. "The role of COL6A5 mutations in the development of myopathy and fibrosis is not understood, but the expression of COL6A5 is decreased in the skin of DSLD-affected horses." (PMID 35866615, 2022).
COL6A5 also shares sentences with these, for which no sentence is quoted: eczema (2 papers); itch (2); psoriatic arthritis (2); allergic asthma (1); allergic disease (1); anaplastic large cell lymphoma (1); benign adenomas (1); breast carcinoma (1); Chiari malformation type I (1); chronic obstructive pulmonary disease (1); early onset hypertension (1); entropion (1); gastric tumors (1); Hypertension (1); inflammatory skin disease (1); Inguinal hernia (1); lung squamous cell carcinoma (1); Osteopenia (1); overnutrition (1); renal fibrosis (1); squamous cell carcinoma (1); Stroke (1); triple-negative breast carcinoma (1); vitiligo (1).